METTL16 (methyltransferase 16, RNA N6-adenosine)
Diseases named in the same sentence as METTL16 in open-access papers (continued):
Sharing a sentence is not in itself a finding about the gene and the disease.
tumor (continued). "Most current studies focus on METTL16’s role in tumor cell proliferation, autophagy, and chemosensitivity, whereas its involvement in immune cell differentiation, infiltration, and immunosuppressive or activating pathways remains underexplored." (PMID 41322419, 2025). "By orchestrating these immune processes, Mettl16 contributes to the establishment of an immunosuppressive tumor microenvironment that hampers the effectiveness of immunotherapies." (PMID 39911396, 2025). "This promotes tumor development, highlighting the METTL16–MYC–GLUL–YTHDC1 axis as a key pathway in Cr(VI)-induced carcinogenesis and suggesting METTL16 as a potential therapeutic target for environmentally related cancers." (PMID 41322419, 2025). "The novel m6A methyltransferase METTL16 has emerged as a key regulator, modulating the expression of critical target genes and signaling pathways, thereby affecting tumor cell proliferation, chemotherapy sensitivity, and the TME." (PMID 41322419, 2025). "Through both m6A-dependent and -independent mechanisms, METTL16 modulates RNA splicing, stability, translation efficiency, and metabolic homeostasis, thereby influencing tumor cell proliferation, invasion, metastasis, and immune evasion." (PMID 41322419, 2025). "Changes in METTL16 expression also correlate with global m6A modification levels, indicating an m6A-dependent tumor-suppressive mechanism." (PMID 41322419, 2025). "The regulatory role of METTL16, which suppresses the malignant phenotype of GC cells at both the transcriptional and post‐transcriptional levels, offers new prospects for tumor diagnosis and precision treatment." (PMID 40095756, 2025). "METTL16, as described in our review, demonstrates dual functionality across cancer types, acting as either a tumor suppressor or an oncogene depending on cellular context, TME, and specific downstream targets." (PMID 41322419, 2025). "As shown, METTL16 knockdown reduced tumor growth and weight, whereas METTL16 overexpression increased tumor growth and weight." (PMID 39744432, 2025). "Subsequently, to understand the pathophysiological role of METTL16 in vivo, we established subcutaneous xenograft tumor models with stable METTL16 overexpression or METTL16 knockdown in BCPAP and K1 cells, where palpable tumors were formed around the 5th day." (PMID 38334797, 2024). "METTL16 KO-mediated inhibition of pre-rRNA processing results in a significant decrease of nucleolar numbers in tumor cells." (PMID 38302992, 2024). "Forced METTL16 expression significantly decreased tumor growth, as indicated by decreased tumor size and weight, which led to a decreased level of Ki-67." (PMID 38334797, 2024). "This is substantiated by the fact that forced expression of eIF3a can largely rescue METTL16 KO-mediated anti-tumor phenotypes, including inhibition of tumor growth and liver CSC self-renewal." (PMID 38302992, 2024). "METTL16 overexpression significantly inhibited tumor growth and metastasis (P<0.001) by downregulating CAPN2 through an indirect mechanism involving the transcription factor TBP and the gene MROH8." (PMID 39434688, 2024). "Consistently, METTL16 level is also significantly higher in the CD133+ CSCs of primary HCC tumors than in the CD133− tumor cells." (PMID 38302992, 2024). "In conclusion, our findings indicate that METTL16 has a tumour‐promoting effect in the progression of CRC." (PMID 38084791, 2024). "The in vivo murine subcutaneous tumor and metastasis model were constructed to further confirm the action of METTL16." (PMID 39061113, 2024). "Analysis of the TCGA database showed that in addition to METTL3 and METTL14, the expression of the novel “m6A writer” METTL16 was also decreased in tumor tissue." (PMID 38334797, 2024). "METTL16 promotes tumor growth and metastasis by regulating the expression of genes involved in cell proliferation, survival, and migration." (PMID 39101773, 2024).
tumor (continued). "As suspected, METTL16 knockdown significantly promoted tumor growth (P<0.001), while METTL16 overexpression significantly inhibited tumor growth (P<0.001)." (PMID 39434688, 2024). "As expected, METTL16 KO suppressed HCC tumor formation and growth, significantly decreased the liver CSC frequency and attenuated the expression of liver CSC markers in vivo." (PMID 38302992, 2024). "METTL16 overexpression markedly inhibited tumor liver metastasis, as measured by the size and number of nodules in the liver." (PMID 38334797, 2024). "In the cytoplasm, METTL16 promotes the assembly of 80 S ribosomes by directly binding to eIF3a/b and rRNAs, thereby promoting protein translation efficiency and tumor development." (PMID 37420298, 2023). "METTL16 plays a tumor-suppressive role and suppresses PDAC cell proliferation through the p21 pathway by mediating m6A modification." (PMID 37182151, 2023). "Su and colleagues found that METTL16 had the most crucial effect on the survival of tumor cells among all METTL protein families." (PMID 37437245, 2023). "Although previous studies have shown the function of METTL16 in mouse embryonic development, the biological roles of METTL16 in diseases, especially tumor progression, are not well understood." (PMID 37340443, 2023). "At the same time, functional assays in vivo also observed that low levels of METTL16 expression promoted tumor growth in EOC xenografts in mice." (PMID 37927399, 2023). "The expression of METTL16 in CCA was examined by analyzing publicly available datasets or by IHC staining on tumor samples." (PMID 37817227, 2023). "Our data showed that depletion of METTL16 by GampeR ASO enhances the tumor inhibitory effect of the FGFR4 inhibitor BLU-554." (PMID 37817227, 2023). "We observed that overexpression of METTL16 suppressed the tumor size and tumor growth curve and enhanced the tumor suppressive effect of anti-PD-1 antibody." (PMID 37647025, 2023). "In vitro and in vivo experiments demonstrated that METTL16 promoted CRC tumor growth depending on its m6A catalytic activity." (PMID 37340443, 2023). "We discovered that METTL16 knockdown dramatically increased the tumor progression compared to that of control cells, as shown by increased tumor weight and volume." (PMID 37927399, 2023). "While the FGFR4 inhibitor BLU-554 or the METTL16 GapmeR ASO alone was able to inhibit CCA cell growth, we found that combinational use of both the FGFR4 inhibitor BLU-554 and the METTL16 GapmeR ASO exhibited more tumor inhibitory effect." (PMID 37817227, 2023). "In summary, our study demonstrates that the regulation of METTL16 and its m6A modifications inhibit pancreatic carcinogenesis by regulating the expression and stability of critical tumor suppressor genes at the posttranscriptional level." (PMID 37182151, 2023). "Increased expression of METTL16 correlated significantly with the tumor size, lymph node metastasis, distant metastasis, and clinical stage grade." (PMID 37340443, 2023). "METTL16 plays a more critical role in almost all tumor cells as an oncogenic gene compared to METTL3 and METTL14." (PMID 37437245, 2023). "The results from in vivo experiments presented synergetic tumor suppressive effects of METTL16 overexpression and PD-1 inhibition." (PMID 37647025, 2023). "Other studies have associated METTL16 with the maturation of MALAT1 mRNA which can act as an oncogene and a tumour suppressor in different types of cancer." (PMID 33461542, 2021). "In vitro and in vivo experiments confirmed that METTL16 promoted proliferation of GC cells and tumour growth." (PMID 34075693, 2021). "YTHDF1, KIAA1429, HNRNPC, and METTL3 were most significantly upregulated in tumor samples, and METTL16 and METTL14 were markedly downregulated." (PMID 34975871, 2021). "When compared with control, we found that METTL16 depletion inhibited tumour growth, along with reduced tumour volume and mass." (PMID 34075693, 2021).
tumor (continued). "Conversely, several m6A regulators, such as ALKBH5 and METTL16, presented tumor-suppressing characteristics, with higher gene expression levels relating to favorable prognosis." (PMID 35046996, 2021). "Advancing our understanding of METTL16's mechanisms not only deepens insights into the significance of RNA modifications in tumor metabolic reprogramming and epigenetic regulation but also suggests novel avenues for its potential use as a therapeutic target or molecular diagnostic marker." (PMID 41459114, 2026). "Additionally, METTL16 can modulate tumor progression by altering the structural and functional integrity of the genome, further emphasizing its potential as a pivotal regulator in cancer biology." (PMID 41459114, 2026). "METTL16 may influence the recruitment, activation, or function of tumor-infiltrating immune cells, thereby shaping the immune landscape within the tumor microenvironment." (PMID 41459114, 2026). "This suggests that METTL16 may regulate the tumor microenvironment by influencing specific immune cell populations, potentially affecting tumor immune evasion and modulating anti-tumor immune responses." (PMID 41459114, 2026). "For instance, METTL16 inhibition could be combined with PARP inhibitors in tumors deficient in homologous recombination repair, potentially resulting in tumor-selective lethality." (PMID 41459114, 2026). "The role of METTL16 in tumor cells extends beyond m6A modification-dependent mechanisms." (PMID 41459114, 2026). "METTL16-mediated modifications or interactions may affect the stability, localization, or activity of oncogenic or tumor-suppressive lncRNAs, thereby influencing gene expression programs and cellular phenotypes associated with cancer progression." (PMID 41459114, 2026). "While the role of METTL16 in ferroptosis during tumor progression is not yet fully understood, further studies are required to determine whether METTL16 influences tumor growth by modulating cellular antioxidant capacity." (PMID 40271153, 2025). "In glioma, METTL16 knockdown inhibits tumor cell migration and invasion while inducing ferroptosis." (PMID 41322419, 2025). "Moreover, Mettl16 regulates other immune cell populations, including regulatory T cells (Tregs), which play a central role in immune tolerance and tumor immune evasion." (PMID 39911396, 2025). "LNP/siMETTL16 efficiently silences METTL16 and markedly suppresses tumor cell activity." (PMID 41322419, 2025). "However, the precise mechanisms by which METTL16 regulates cancer immunity remain largely unclear, with most current studies focusing on in vitro systems or single tumor models." (PMID 41322419, 2025). "Oncogenic and tumor-suppressive functions of METTL16 across cancers." (PMID 41322419, 2025). "Conversely, METTL16 also exhibits tumor-suppressive functions in certain contexts." (PMID 41256854, 2025). "In recent years, RNA m6A modification has emerged as an important regulator in GC tumorigenesis, with the novel m6A methyltransferase METTL16 potentially modulating tumor proliferation, metastasis, and therapy resistance through regulation of key target genes and signaling pathways." (PMID 41322419, 2025). "In metal-induced carcinogenesis, studies have shown that METTL16 expression is significantly upregulated in LC cells and mouse tissues exposed to hexavalent chromium [Cr(VI)] and plays a critical role in Cr(VI)-induced cell proliferation and tumor growth." (PMID 41322419, 2025). "METTL16 serves as a favorable prognostic biomarker because of its association with improved survival outcomes, whereas METTL3 may influence tumor progression through RNA metabolic reprogramming." (PMID 40986143, 2025). "METTL16 may regulate the expression of immune checkpoint-related genes in an m6A-dependent manner, influencing tumor immune surveillance and the efficacy of immunotherapy." (PMID 41322419, 2025). "This METTL16–MALAT1–β-catenin axis mediates the tumor-suppressive effects of METTL16 in OV." (PMID 41322419, 2025).
tumor (continued). "METTL16 is a methyltransferase demonstrated to be upregulated in malignancies such as hepatocellular carcinoma, breast cancer, and gastric cancer, promoting tumor growth, invasion, and metastasis." (PMID 40243425, 2025). "Recent studies indicate that RNA m6A modification plays a critical role in OV development, with the novel m6A methyltransferase METTL16 potentially regulating tumor proliferation, metastasis, and chemoresistance through modulation of key gene expression and signaling pathways." (PMID 41322419, 2025). "Hence, we used RNA and TMA of our own patients and found that PMEPA1 was remarkably higher expressed in tumor tissues than in adjacent tissues, while METTL16 was negatively correlated with PMEPA1 expression." (PMID 38385084, 2024). "Notably, experimental investigations confirmed that METTL16 suppression facilitated invasive tumor characteristics through the activation of the Notch signaling cascade." (PMID 39101773, 2024). "As referred before, cyclin D1 may facilitate tumor growth as a downstream effector of METTL16 in GC." (PMID 39009956, 2024). "Finally, we found that hypoxia-inducible factor 2α (HIF-2α) exerted its tumor-promoting effect by binding the METTL16 promoter region to repress its transcription." (PMID 38385084, 2024). "Moreover, reported showed that METTL16 level is enhanced in BC tissues and its inhibition lessened the tumor growth of BC in vivo." (PMID 39061113, 2024). "Collectively, these results revealed that METTL16 might be a tumor suppressor in PTC through its m6A writer function." (PMID 38334797, 2024). "Using the METTL family as an example, the analysis of data obtained from The Cancer Genome Atlas (TCGA) database revealed that increased expression of METTL16 is significantly correlated with tumor size, lymph node metastasis, distant metastasis, and clinical stage grading in CRC." (PMID 39468015, 2024). "Moreover, SCD1 expression and TG accumulation were decreased in the K1 tumor xenograft model overexpressing METTL16 but increased with METTL16 knockdown." (PMID 38334797, 2024). "More interestingly, we collected the protein samples from HDTVi-HCC tumors and their adjacent normal liver tissues and found that Mettl16 abundance is much higher in HDTVi-HCC tumors than normal liver tissues, reiterating the tumor-promoting role of Mettl16 in de novo hepatocarcinogenesis." (PMID 38302992, 2024). "Our findings indicate a tumor-promoting role of METTL16 in CRC progression." (PMID 37340443, 2023). "This suggests that targeting METTL16 is expected to be a potential new strategy for tumor therapy." (PMID 37420298, 2023). "However, in our study, we revealed for the first time that the novel m6A writer METTL16 was significantly decreased in PC cells and played a tumor suppressor role during human pancreatic carcinogenesis and progression." (PMID 37182151, 2023). "The results of KEGG suggested that the majority of the genes that were significantly associated with the expression of METTL16 and lncRNA MALAT1 were enriched in the Wnt/β-catenin pathway, clarifying that METTL16 possibly plays its tumor suppressive role through inhibiting the Wnt/β-catenin pathway." (PMID 37927399, 2023). "In parallel, we had employed a separate CCA xenograft model in which human CCA cells were inoculated into the livers of NOD/SCID mice; we observed that deletion of METTL16 by CRISPR/Cas9 also significantly inhibited CCA growth when the tumor cells were inoculated into the livers." (PMID 37817227, 2023). "Moreover, the levels of CD4 and CD8 positive cells in tumor tissues were notably elevated by overexpression of METTL16 and anti-PD-1 treatment compared with the control group and were further increased by their combination." (PMID 37647025, 2023). "A comprehensive study about the regulation and function of METTL16 may therefore provide better insights into the prevention of tumor therapy and metastasis." (PMID 37863889, 2023).
tumor (continued). "Therefore, our study on METTL16-mediated m6A regulation of tumor progression is novel and of great significance." (PMID 37182151, 2023). "Analysis on tumor tissues demonstrated that overexpression of METTL16 and blocking of PD-1 could notably suppress the expression of proliferative biomarker Ki-67." (PMID 37647025, 2023). "Herein, we found that METTL16 plays a crucial tumor-promoting role in CRC." (PMID 37340443, 2023). "Endogenous METTL16 located in the nucleus in GC tumor cells." (PMID 37863889, 2023). "Moreover, METTL16 knockdown decreased the expression of Ki67, a biomarker of tumor proliferation, whereas METTL16 overexpression promoted Ki67 expression in vivo." (PMID 37340443, 2023). "In vitro and in vivo experiments indicated that METTL16 served as a tumor suppressor in PDA." (PMID 36158188, 2022). "Further, Gene Ontology and Kyoto Encyclopedia of Genes and Genomes analyses revealed that METTL16 may have an effect on the tumor microenvironment." (PMID 36158188, 2022). "Collectively, these findings highlight the prognostic value of METTL16, and indicate that it is a potential immunotherapy target that could be used to regulate the tumor microenvironment and promote antitumor immunity in PDA." (PMID 36158188, 2022). "In addition, we performed immunofluorescence staining in the tumour tissue sections of xenograft mice and found that cyclin D1 expression was dramatically inhibited in the METTL16 knocked down group." (PMID 34075693, 2021). "The results suggest that expression of ALKBH5, IGF2BP2, METTL16, AL513165.1, and AP005233.2 is significantly associated with tumor stage and that expression of UCA1, IGF2BP2, METTL16, AL513165.1, AP005233.2, and AC099850.3 is significantly associated with tumor grade." (PMID 34233576, 2021). "In this study, we found that METTL16 knock‐down could inhibit GC cell proliferation and tumour growth in mice, and the total m6A level of RNA was reduced in METTL16 knocked down or methyltransferase inhibitor–treated GC cells, including AGS, MGC803 and SNU719." (PMID 34075693, 2021). "In addition to small molecules, RNA interference technologies, such as small interfering RNA (siRNA) or short hairpin RNA (shRNA), can be used to knock down METTL16 expression in cancer cells, potentially leading to further suppression of tumor growth and metastasis." (PMID 41459114, 2026). "Overexpression of METTL16 has been shown to significantly reduce the proportion of PD-1-positive cells in activated T cells, suggesting that METTL16's regulatory activity may reduce immune evasion and enhance the immune system's ability to recognize and attack tumor cells." (PMID 41459114, 2026). "METTL16 may regulate the production or secretion of cytokines, chemokines, and other immune mediators, thereby modulating immune cell trafficking, inflammation, and interactions within the tumor microenvironment." (PMID 41459114, 2026). "Additionally, METTL16 may participate in tumor immune regulation by modulating immune cell function within the TME, providing a theoretical rationale for combination therapies with immune checkpoint inhibitors or other immunotherapies." (PMID 41322419, 2025). "RNA modifications can be catalyzed, erased and recognized by methyltransferases such as METTL1, METTL3, METTL16, and accurately regulate the process of methylation, which plays an important role in the proliferation, metastasis, invasion, apoptosis, autophagy, and drug-resistance of tumor cells." (PMID 40443650, 2025). "Therefore, the results indicated that expression of METTL16 was correlated with immune infiltration in cancers, which may lead to the development of related tumor diseases." (PMID 40015977, 2025). "Moreover, METTL16 exhibits tissue- or cell-specific expression patterns in certain tumor types, and its stable expression profile may provide a basis for early diagnosis." (PMID 41322419, 2025). "Moreover, knockdown of METTL16 significantly inhibited tumor growth and migration." (PMID 39247832, 2024).